DNMT3A (DNA methyltransferase 3 alpha)
Diseases named in the same sentence as DNMT3A in open-access papers (continued):
Sharing a sentence is not in itself a finding about the gene and the disease.
hematological malignancies (65 papers, 2013 to 2026). "Mutations in the R882 residue of DNMT3A are predominant in a broad range of hematological malignancies." (PMID 39537978, 2025). "Mutations of Dnmt3a in patients with hematologic malignancies were associated with gene expression alterations of canyon genes." (PMID 39819598, 2025). "CH is typically defined by pathogenic driver mutations associated with hematological malignancies, most commonly in the epigenetic regulators DNMT3A, TET2, and ASXL1, which collectively account for 90% of CH cases." (PMID 37083525, 2023). "DNMT3A mutations are present in approximately 10%–20% hematological malignancies, with the R882 site being a unique mutation hotspot, conferring dominant-negative inhibition against the wild-type DNMT3A enzyme and poor prognosis." (PMID 37072414, 2023). "Heterozygous mutations in FLT3ITD, TET2, and DNMT3A are associated with hematologic malignancies in humans." (PMID 36073548, 2022). "TET2 and/or DNMT3A was mutated in human solid tumors as well as in hematological malignancies to a greater degree." (PMID 34039392, 2021). "The TBRS mutations are specifically localized in each of the three functional domains of DNMT3A, 11 of which overlap with the somatic DNMT3A variants found in hematological malignancies." (PMID 31091831, 2019). "What is clear from this review is that while mutations in DNMT3A play a significant role in the development of haematological disorders such as AML and MDS, understanding of the mechanisms and downstream consequences of such mutations is still undetermined." (PMID 28286768, 2017). "It is catalyzed by DNA methyltransferases, one of which -DNMT3A- is frequently mutated in human hematologic malignancies." (PMID 27677595, 2016). "Given the large magnitude of promoter hypomethylation observed in various mouse hematologic malignancies, it is possible that loss of Dnmt3a and Dnmt3b maintenance activity drives tumorigenesis due to the inappropriate expression of genes normally silenced." (PMID 27563627, 2016). "Somatic recurrent DNMT3A mutations have been identified in multiple types of human hematological malignancies, thus linking loss of DNMT3A enzymatic function directly with tumorigenesis." (PMID 27462454, 2016). "In AML, DNMT3a plays a crucial role since more than 20% of patients exhibit DNMT3A mutation, conferring a global hypomethylation of DNA and predisposition to developing hematological diseases." (PMID 26955619, 2016). "DNMT3A mutations are frequent in elderly people with clonal hematopoiesis of indeterminate potential (CHIP) or clonal cytopenia of undetermined significance (CCUS) who are at increased risk of developing hematological malignancies." (PMID 40151616, 2025). "However, with the advent of the CRISPR base-editing technology, it is now possible to introduce point mutations and other sequence variations, as demonstrated in case of the residue R882, the mutational hotspot of DNMT3A linked to hematologic malignancies." (PMID 39819598, 2025). "Given the frequent studies reporting the hypomethylation of DDX43 promoter in hematological malignancies, and the significance of R882H mutations in DNMT3A, we hypothesized that there may be some relations between these two events." (PMID 38807916, 2024). "Next, we sought to replicate our primary findings from the UK Biobank and establish whether the presence of co-occurring mCA and JAK2/DNMT3A impact the risk of subsequent development of hematologic malignancies (HM)." (PMID 38225345, 2024). "Additionally, DNMT3A mutations have been linked to a higher risk of developing hematological disease and to poorer outcomes in both AML and MM patients." (PMID 38667272, 2024). "In fact, in some studies, the same DNMT3A mutation as the antecedent hematologic disorder is identified in secondary AML, suggesting that these mutations may be an early event in malignant clonal evolution." (PMID 36119476, 2022).
hematological malignancies (continued). "In addition to revealing the proapoptotic effect of oridonin, our study provides evidence for the first time that necroptosis participates in the cell death induced by oridonin in hematological malignancies with DNMT3A mutations." (PMID 34663800, 2021). "DNMT3A is one of the most commonly mutated genes in adult hematologic malignancies." (PMID 29326230, 2018). "In addition to roles in normal B cell development, experimental and human sequencing data point to a role for DNMT3A mutation and/or loss-of-function in hematologic disease." (PMID 29326230, 2018). "Moreover, miR-10a and HOXB4 overexpression seemed associated with DNMT3A mutation in hematological malignancies." (PMID 30419846, 2018). "Therefore, it was proposed that DNMT3A mutation is relevant for initiating hematopoietic stem cell clonal expansion and an early initiation event for hematological malignancies." (PMID 29619119, 2018). "Furthermore, it has been shown that DNMT3A is the most frequently mutated gene in clonal hematopoiesis of the elderly and this was linked to a higher risk for hematological malignancies—indicating that aberrations in DNMT3A play a central role for clonal hematopoiesis." (PMID 30582132, 2018). "Previous research has shown that ITP patients harboring mutations in genes such as DNMT3A, TET2, ASXL1, BCOR, PIGA, and U2AF1 tend to progress into other clonal hematologic disorders, leading to treatment ineffectiveness." (PMID 40574285, 2025). "In particular, the loss of DNMT3A and TET2 function is conspicuous in diverse hematological disorders, including myeloid and lymphoid malignancies, and causally related to clonal hematopoiesis and malignant transformation." (PMID 36675240, 2023). "DNMT1 has been a focal point for mechanistic studies Involving decitabine and bortezomib in hematological malignancies, nevertheless mechanisms regarding DNMT3a and DNMT3b activity remain largely unclear upon treatment with these drugs." (PMID 34358067, 2021). "DNA methylation and specifically DNA methyltransferase enzyme DNMT3A, involved in de novo methylation, modulates pathogenesis of various hematological diseases and is involved in regulating the function of immune cells." (PMID 33803981, 2021). "Intriguingly, in comparison to the previous analysis, we observed 6 new non-synonymous SNVs linked to hematological disease, including variations in CBL (1 pt); DNMT3A (3 pts); FLT3 (1 pts), NQO1 (1 pt); NRAS (1 pts) and 2 frameshifts: CEBPA (1 pts) and NBN (1 pts)." (PMID 38612443, 2024). "However, because DNMT3A and ASXL1 often contain somatic mutations in a variety of adult hematologic malignancies, we chose to exclude these variants from subsequent analyses." (PMID 37762649, 2023). "Detection of these highly clonal, co-occurring CH events, especially at TET2, DNMT3A, and JAK2, could be helpful in identifying individuals at increased risk of developing hematologic malignancies." (PMID 37684235, 2023). "To date, several additional DNMT3A mutations have also been associated with the development of hematological malignancies in both humans and mice with TBRS, suggesting germline DNMT3A mutations may also promote clonal hematopoiesis and AML." (PMID 37947606, 2023). "However, the functional relevance of Dnmt3a for hematopoietic differentiation and hematological malignancies has mostly been analyzed in mice, with the specific role for human hematopoiesis remaining elusive." (PMID 35705990, 2022). "Two large studies on CHIP were used to retrieve DNMT3A mutations in individuals without hematologic malignancies." (PMID 35296003, 2022).
hematological malignancies (continued). "Mutations at the DNMT3A gene, encoding for the DNA methyltransferase 3 alpha, have been also described; however, the recurrence of this genetic alterations in JMML is lower than in other hematologic malignancies." (PMID 35267643, 2022). "Somatic mutations within DNMT3A have been identified in up to 17% of T-ALL cases in adults and have been associated with the immature subtypes and with the older age of patients with hematological malignancies." (PMID 33573325, 2021). "However, under some circumstances Dnmt3a has acted as an oncogene by promoting the development of hematologic malignancies." (PMID 27563627, 2016). "Recurrent mutations in DNMT3A have been associated with adult hematologic malignancies, and mice lacking Dnmt3a die within the first weeks of postnatal life." (PMID 23552396, 2013). "Thus, the anticancer efficacy of CBL0137 in hematological malignancies may be partially mediated by the inhibition of DNMT3A, but this mechanism needs further investigation." (PMID 37629054, 2023). "Importantly, none of mice in this study did develop hematological malignancy, which suggested that mutation in Dnmt3a is not a potent leukemogenic driver." (PMID 33573325, 2021). "For example, DNMT3A correlated with Nelarabine, which is an FDA approved drug and is used for the treatment of hematologic malignancies." (PMID 38277218, 2024). "In elderly people without hematologic disorders DNMT3A mutant clones are unlikely to expand over time, which supports the finding of stable VAFs under TKI therapy in CML patients." (PMID 35902731, 2022). "While the work here is focused on ESCs, these findings may have relevance for the role of DNMT3A and TET2 in hematologic malignancies." (PMID 30001199, 2018).
infection (30 papers, 2011 to 2025). The state of being infected such as from the introduction of a foreign agent such as serum, vaccine, antigenic substance or organism. "The previous 9 patients shared recurrent somatic mutations (ASLX1, DNMT3A) and karyotype abnormality (monosomy 7), and all survived after receiving hematopoietic stem cell transplantation, except one case who died of infection after transplantation." (PMID 39614632, 2024). "Mice deficient for Dnmt3a showedgreater susceptibility to infection by vesicular stomatitis virus (VSV)." (PMID 32022099, 2020). "It has recently been shown that activated IFNγ signaling, in the experimental context of infection or exogenous administration, is a strong driver of the clonal expansion of cells carrying loss-of-function mutations in the gene DNMT3A, by far the most prevalent mutation found in CH." (PMID 36496394, 2022). "In contrast, infection with AAV‐Dnmt3a resulted in significant overexpression of DNMT3a protein in both PTX‐treated (Dnmt3a + PTX) and vehicle‐treated (Dnmt3a + vehicle) groups." (PMID 39679872, 2025). "Genes that encode products involved in innate immunity and are regulated by DNMT3A and DNA methylation have the potential to be targeted for drug discovery in diseases related to infection." (PMID 38643118, 2024). "This suggests that long-term infection disrupts de novo methylation (via DNMT3A gene deregulation) and maintenance of methylation during cell proliferation (via DNMT1 gene deregulation)." (PMID 35531332, 2022). "Dox was added 2–4 days post-infection to allow for degradation of Dnmt3a mRNA and protein before inducing Ascl1 expression for direct conversion of MEFs to neurons." (PMID 30644360, 2019). "Levels of DNMT1 mRNA fell markedly at 6 h post-infection, while those of DNMT3a and DNMT3b fell only slightly at 12 h post-infection." (PMID 29717211, 2018). "We observe mild differences for the other DNMTs between the original, uninfected HUES48 and the infected cell lines (shRNA control and shRNA DNMT3A), which are likely due to clonal expansion post infection." (PMID 22174693, 2011). "We found that BATF2 was differentially regulated in response to infection in Dnmt3a-KO mice." (PMID 40905954, 2025). "Interestingly, we and others showed that loci encoding transcription factors such as Batf2, Fos, and Jun, important in myeloid differentiation were hypermethylated and transcriptionally repressed in Dnmt3a-mutant HSCs after infection." (PMID 40905954, 2025). "Furthermore, as expected, Western blotting indicated that DNMT3A expression was remarkably reduced after infection with DNMT3A-sgRNA lentivirus." (PMID 36934225, 2023). "Herpes simplex virus type 1 (HSV-1) capsid protein VP26 was identified to bind to the host factor de novo DNA methyltransferase DNMT3A during infection, and downregulating DNMT3A with siRNA or suppression by the human DNMT inhibitor RG108 can dramatically trigger a decrease in HSV-1 titres." (PMID 35335337, 2022). "Overexpression of Dnmt3a by lentivirus infection confirmed that Dnmt3a significantly inhibited the expression of osteogenic-related genes and Wnt/β-Catenin signaling pathway in DOP-ASCs and the osteogenic differentiation ability of DOP-ASCs was restored after inhibition of Dnmt3a." (PMID 35927735, 2022). "To investigate the effect of Dnmt3a on the proliferation ability of Jak2V617F BaF3 cells, we constructed Dnmt3a silencing and overexpression plasmids, and the corresponding stably transformed Jak2V617F BaF3 cell lines were constructed using lentiviral infection techniques." (PMID 34773997, 2021). "At 3 days post infection, we found a small but significant decrease in the MFI of Dnmt3a within DAC treated SMARTA cells." (PMID 39677644, 2025). "To determine if DAC treatment impaired Dnmt3a-mediated methylation programing, we performed WGEM-seq on Tfh and Th1 cells from PBS or DAC treated mice at 7 days post infection." (PMID 39677644, 2025).
infection (continued). "In our result, we have shown a significant decrease in levels of DNMT1, DNMT3A, and DNMT3B following SARS-CoV-2 in vitro infection." (PMID 33679887, 2021). "Recently, it was also shown that following infection of germinal centre (GC) B cells, EBV down-regulates DNMT1 and DNMT3B expression, whilst upregulating DNMT3A." (PMID 23189137, 2012). "Furthermore, we upregulated HDAC7 in DNMT3a knockdown LUAD cells and downregulated HDAC7 in DNMT3a overexpression LUAD cells by lentivirus infection." (PMID 39990668, 2025). "Next, expression of these three DNMTs protein was detected by western blotting; the results were consistent with mRNA levels, showing that DNMT1, but not DNMT3a and DNMT3b, protein was down-regulated obviously at 12 h post-infection." (PMID 29717211, 2018). "At every 24 hours within 4 days after lentiviruses infection of SiHa and CaSki, we used Q-PCR to analyze the expression of E6, E7, DNA methyltransferase genes (DNMT1, DNMT3A, DNMT3B and DNMT3L), and tumor suppressor genes (MT1G, NMES1, RRAD, SFRP1, SPARC and TFPI2)." (PMID 26329329, 2015). "To determine genes where Dnmt3a may silence expression via de novo methylation in primary effector cells, we performed RNA sequencing on Tfh and Th1 cells sorted from LCMV infected mice at 7 days post infection." (PMID 39677644, 2025). "To determine whether Dnmt3a was necessary for de novo methylation at genes associated with alternative T helper lineages, we performed whole genome enzymatic methylation sequencing (WGEM-seq) on WT and Dnmt3a KO (CD4-Cre) Tfh and Th1 cells sorted from LCMV infected mice at 7 days post infection." (PMID 39677644, 2025). "In addition, LANA has been shown to interact with a number of host epigenetic factors (e.g. KAP1, mSin3, DNMT3a, KDM3A, Tip60, and hSET1), which may also be involved in the timing of PRC2 recruitment to the viral episome during de novo infection." (PMID 27606464, 2016). "Quantitative measurement of the mRNAs of DNMT1 DNMT3a and DNMT3b by real-time qRT-PCR reveals that the mRNAs of all the three major form of DNMTs are present in PT cells and PPV infection does not change their levels significantly." (PMID 24392033, 2013).
cardiovascular disease (22 papers, 2019 to 2025). "Clinical studies in patients with cardiovascular disease have identified DNMT3A, TET2, and ASXL1 genes as the most commonly mutated CHIP-driver genes, accounting for ~80% of all CHIP cases." (PMID 40278194, 2025). "It appears that the presence of DNMT3A‐driven CHIP causes an excessive inflammatory response in patients with cardiovascular disease." (PMID 39006763, 2024). "In patients with TET2 and DNMT3A clonal hematopoiesis, an inflammasome hyperactivation in myeloid cells was noticed, which represents the potential cause of cardiovascular disease." (PMID 37915324, 2023). "Mechanistically, DNMT3A/TET2 CHIP‐driver mutations may exert their detrimental effects on cardiovascular disease predominantly by a pro‐inflammatory activation of circulating blood cells." (PMID 40702883, 2025). "Meanwhile, patients with CHIP, represented by JAK2V617F mutation, had a 12.1-fold increase in cardiovascular diseases (CADs), while CHIP sustained by DNMT3A, TET2, or ASXL1 had a 1.7–2-fold increase in CADs." (PMID 37915324, 2023). "The other T-box transcription factor, TBX5, is involved in cardiovascular development, and inactivating DNMT3A/3A2 contributes to cardiovascular disease." (PMID 35749276, 2022). "In addition to Tet2, mutations in DNA (cytosine-5)-methyltransferase 3A (DNMT3A), Additional Sex Combs-Like 1 (ASXL1) and Janus kinase 2 (JAK2) induce clonal hematopoiesis and cardiovascular disease." (PMID 32823583, 2020). "The bulk of this review discussed the roles of DNMT1, DNMT3A, and DNMT3B in both germline and hematopoietic cells in the development of PAH and cardiovascular diseases." (PMID 37947606, 2023). "The increased mortality associated with carrying DNMT3A- and/or TET2-CHIP-driver mutations is independent of traditional risk factors for cardiovascular disease." (PMID 36680616, 2023). "The roughly twofold increased risk of AKI progressing to dialysis and nonresolving AKI we observed in non-DNMT3A-CHIP clones was similar in magnitude to that observed for CHIP and cardiovascular disease." (PMID 38454125, 2024).